STC2 (stanniocalcin 2)
Diseases named in the same sentence as STC2 in open-access papers (continued):
Sharing a sentence is not in itself a finding about the gene and the disease.
tumor (continued). "Statistically significant relation was found between the STC2 expression and tumor Dukes’ stage (P<0.001)." (PMID 35096084, 2022). "In this study, a statistically significant relation was found between the STC2 expression and tumor N stage (P=0.001)." (PMID 35096084, 2022). "For reference, STC2, a downstream target of miR-361-3p, was shown to promote tumor invasion and migration via the Wnt/β-catenin signaling pathway in vivo experiments, while SNHG17 acts as a ceRNA for miR-361-3p." (PMID 36185210, 2022). "We estimated the relationship between STC2 expression and tumor stemness according to the previous study." (PMID 36685853, 2022). "Under stress conditions such as hypoxia, ER stress, and nutrient deprivation, both transcriptional and post transcription of STC2 were regulated, and in turn drives tumor cell growth, proliferation, and tumorigenesis." (PMID 35937984, 2022). "To evaluate the role of STC2 in the tumor microenvironment, we analyzed the relationship between STC2 expression level and 60 common ICP gene expressions, including 24 inhibitory and 36 stimulatory." (PMID 35937984, 2022). "Clinically, increased STC2 expression is correlated with local invasion, lymphatic metastasis, tumour size and advanced disease stages." (PMID 35501821, 2022). "Two independent whole genome-wise studies identified STC2 as one of the most upregulated genes in RCC tumour tissues relative to adjacent normal kidney." (PMID 35501821, 2022). "Clinicopathological investigations indicate the expression of STC2 is correlated with tumour development, tumour progression and patients’ prognosis." (PMID 35501821, 2022). "It showed that STC2 expression significantly correlated with tumor stage in majority of tumor types like KIRP and THCA, and was associated with tumor grade in KIPAN, HNSC, and KIRC." (PMID 36685853, 2022). "STC2 is upregulated in many tumour cells under multiple stress conditions which activate ATF4, HIF-1 or both, strongly suggesting that STC2 participates in the evolutionarily conserved response under stress conditions." (PMID 35501821, 2022). "Emerging evidence suggests that the aberrant expression of STC2 in tumor tissues is involved in GBM progression; however, the underlying mechanisms are not fully understood." (PMID 35790735, 2022). "Unlike the three GRGs above, the potential role of KIF20A and STC2 in tumor development, progression and prognosis has been widely studied." (PMID 35123420, 2022). "Stanniocalcin 2 (STC2) is a glycoprotein hormone over-expressed in many human cancers where it regulates tumor progression and invasion." (PMID 35096084, 2022). "Stanniocalcin 2 (STC2) is a glycoprotein which is expressed in a broad spectrum of tumour cells and tumour tissues derived from human breast, colorectum, stomach, esophagus, prostate, kidney, liver, bone, ovary, lung and so forth." (PMID 35501821, 2022). "In general, STC2 drives cell proliferation and maintains cell survival in a plethora of tumour cells, particularly for those under stress conditions." (PMID 35501821, 2022). "Up-regulation of STC2 under hypoxia facilitates the adaptation of tumor cells to hypoxia and thus promotes tumor progression." (PMID 36518242, 2022). "This provides a certain basis for bioinformatics analysis for future studies of STC2 in tumor immunity and tumor microenvironment." (PMID 35937984, 2022). "Meanwhile, the effects of copy number variation (CNV) on STC2 expression were investigated across various tumor types, suggesting that STC2 expression was significantly correlated with CNV in tumors." (PMID 36685853, 2022). "Stanniocalcin 2 (STC2) is a glycoprotein hormone involved in many biological processes and a secretory protein that regulates malignant tumor progression." (PMID 34616672, 2021). "This review aims to improve the understanding of the role of STC2 in patient diagnosis and prognosis, and tumor development and progression, as well as the mechanisms involved." (PMID 34612765, 2021).
tumor (continued). "Based on the pivotal findings, further studies are warranted to provide insights into the role of STC2 in cancer biology including metastasis and tumor angiogenesis, and potential as biomarkers and therapeutic targets." (PMID 34612765, 2021). "The STC2 expression was significantly correlated with tumor grade and histological type, and was inversely correlated with patient survival, suggestive of a potential predictor of patient prognosis." (PMID 34612765, 2021). "In mammals, STC2 is widely expressed in many tissues including kidney, ovary, bone, neurones, and muscle, with a role in mineral homeostasis and tumor promotion." (PMID 34612765, 2021). "Meanwhile, the relative expression of CFLAR and STC2 in tumor cells was significantly higher than that in normal cells (all P < 0.05)." (PMID 34225733, 2021). "The expression of STC2 in tumor tissues was related to thyroid cartilage invasion, T-stage, lymphatic metastasis, clinical stage, and pathological differentiation." (PMID 34612765, 2021). "The overexpression of STC2 was correlated with clinical stage, tumor location, and histological grade." (PMID 34612765, 2021). "STC2 expression, tumor diameter, carcinoma emboli in the portal vein, tumor differentiation degree, and tumor stage were independent factors affecting the overall survival of postoperative patients." (PMID 30962272, 2019). "Both STC2 mRNA and protein expression are related to tumor diameter, stage, tumor metastasis, carcinoma emboli in the portal vein and the degree of tumor differentiation in HCC." (PMID 30962272, 2019). "Several studies have shown that hypoxia can induce the high expression of hypoxia-inducible factor-1 (HIF-1) and then stimulate the high expression of STC2, which is helpful to promote tumor cell proliferation and inhibit tumor cell apoptosis." (PMID 30962272, 2019). "Multifactor Cox survival stage showed that STC2 expression, tumor diameter, carcinoma emboli in the portal vein, tumor differentiation degree, and tumor stage were independent factors affecting the overall survival of postoperative patients." (PMID 30962272, 2019). "Numerous studies have examined STC1 and STC2 in the tumor microenvironment, where they have positive effects on tumor migration and invasion." (PMID 29748538, 2018). "Recently, an integrated analysis of high-density copy number and gene expression data for 54 ccRCC tumours identified STC2 (5q35.1) and VCAN (5q14.3) as potential 5q oncogenes in ccRCCs." (PMID 28486536, 2017). "All these findings suggest STC2 is a potential tumor biomarker and a serum biomarker for CRC diagnosis and prognosis." (PMID 27662663, 2016). "The mice injected with cells expressing STC2 cDNA displayed small tumor volumes, while those injected with cells expressing STC2 shRNA developed big tumor volumes, compared with mice injected with control cells." (PMID 25830567, 2015). "STC2 has been reported to be upregulated in a series of cancers and been correlated to tumor progression and prognosis." (PMID 24606961, 2014). "Laboratory animal and cell culture studies are also required to provide mechanistic understanding of the roles of STC2 in tumor progression, metastasis and resistance to radiation therapy (IMRT)." (PMID 24606961, 2014). "In contrast, patients with high levels of STC2 expression in tumor tissues had significantly poorer OS rates than those with negative or low STC2 expression." (PMID 24743310, 2014). "Recent studies demonstrate that mammalian STCs (STC1 and STC2) play important roles in tumor progression." (PMID 24743310, 2014). "Solid tumors frequently develop a hypoxic condition which activates HIF-1 to sustain tumor growth and progression and STC2 is one of HIF-1 target genes." (PMID 24606961, 2014). "Our results showed that circulating STC1 or STC2 mRNA levels were significantly correlated with one or more features indicative of worse tumor biology." (PMID 24743310, 2014).
tumor (continued). "Nevertheless, our data show that STC2 overexpression correlates to NPC progression, which is consistent with previous studies in other solid tumors and with the notion that STC2 overexpression facilitates tumor progression and migration." (PMID 24606961, 2014). "It has been proposed that STC2 overexpression (STC2+) contributes to tumor cell’s adaptation to such stress conditions, thus facilitating tumor progression." (PMID 24606961, 2014). "STC2 expression in tumor tissues significantly correlated with thyroid-cartilage invasion, T-Stage, lymphatic metastasis, clinical stage, and pathological differentiation." (PMID 24743310, 2014). "It has been proposed that STC2 facilitates tumor cell migration through epithelial-mesenchymal transition (EMT) and upregulation of MMP-2 and MMP-9 in hypoxic conditions." (PMID 24606961, 2014). "However, STC2 positive rate was higher in T3-4 than T1-2 with a marginal significance (P=0.050), indicating STC2 overexpression may be positively associated with increased tumor sizes." (PMID 24606961, 2014). "Some clinicopathological studies correlate high expression levels of STC1 and STC2 in human tumor samples with poor prognostic outcomes." (PMID 24743310, 2014). "The identification and functional analysis of STC2 upregulation by hypoxia, a feature of the tumor microenvironment, sheds light on a possible role for STC2 in tumors." (PMID 23548070, 2013). "The finding provides evidence that STC2 is a positive regulator of tumor progression in hypoxic conditions." (PMID 23548070, 2013). "STC2 is also up-regulated in response to hypoxic insult and is expressed to higher levels in many tumor-derived cell lines." (PMID 21545732, 2011). "Interestingly, STC2's expression was also associated with genetic alterations, including microsatellite instability (MSI) and tumor mutational burden (TMB), highlighting its potential involvement in genomic instability, a hallmark of cancer." (PMID 40535801, 2025). "In this context, STC2 overexpression may support cell survival by upregulating pathways that protect the tumor from the cytotoxic effects of treatment, leading to a poor chemotherapy response." (PMID 40006048, 2025). "Moreover, the relationship between STC2 expression and immune infiltration underscores its possible role in modulating the tumor immune microenvironment, which is a crucial aspect of tumor progression and response to therapy." (PMID 40535801, 2025). "Furthermore, estrogen-induced upregulation of STC2 reportedly inhibits AMPK activity and promotes tumor growth, whereas STC2 knockdown restores AMPK phosphorylation and reduces EC cell viability." (PMID 40806980, 2025). "Moreover, their multivariate analysis data highlighted both STC2 expression and tumor grade as independent predictors of disease recurrence." (PMID 39186548, 2024). "Moreover, our prior study found STC2 was also upregulated by hypoxia, suggesting STC2 induction is a common phenomenon when tumour cells exposed to nutrient insufficiency." (PMID 39107307, 2024). "The analysis revealed higher STC2 expression in 18 tumor types." (PMID 38229155, 2024). "More importantly, larger necrotic areas were observed in STC2 knockdown xenografts compared to control ones, suggesting a failed adaptation to insufficient blood supply during tumour progression, which is consistent with a previous report that STC2 was involved in tumour angiogenesis." (PMID 38464261, 2024). "Under nutrient insufficient conditions, STC2 slows down cell proliferation that might be more beneficial for tumour cells by allocating limited resources to fulfill their basic demands, such as maintaining cell survival." (PMID 38464261, 2024). "Next, we asked how STC2 protects tumour cells from nutrient insufficiency-induced apoptosis." (PMID 38464261, 2024).
tumor (continued). "Under nutrient-insufficient conditions, STC2 slows down cell proliferation which might be more beneficial for tumour cells by allocating limited resources to fulfil their basic demands, such as maintaining cell survival." (PMID 39107307, 2024). "Interestingly, previous studies indicate that STC2 is involved in several malignant tumor processes and is upregulated in various cancers, leading to poorer outcomes." (PMID 39020010, 2024). "Moreover, STC2 knockdown xenografts overall had lighter tumour weights compared to control counterparts." (PMID 38464261, 2024). "We found that STC2 knockdown tumours grew slower than control ones." (PMID 38464261, 2024). "STC2 expression has been correlated with tumor stage and survival time in CRC patients." (PMID 37580737, 2023). "STC2 has a vital role in cell–cell interactions between normal colon epithelia and tumor cells." (PMID 37580737, 2023). "STC2 is a glycoprotein with high expression in various tumor cells." (PMID 38001121, 2023). "Consistently, STC2 inhibition suppressed the growth and invasion of GC cells indicating that miR-184 may play a tumor suppressor role." (PMID 38001121, 2023). "Altogether, these results suggest that tumor-secreted STC2, as well as intracellular STC2, may induce neighboring cells to become more malignant." (PMID 35790735, 2022). "Ke and his colleagues proposed the tumor-promoting mechanism of miR-1-3p/STC2 axis in GC." (PMID 35346060, 2022). "Nude mice model results showed that knockdown of STC2 significantly inhibited tumor growth." (PMID 33797657, 2022). "STC2 could regulate drug efflux and drug resistance of tumor cells by regulating the expression levels of P-glycoprotein and Bcl-2 protein." (PMID 35937984, 2022). "cDNA microarray analysis demonstrated the upregulation of STC2 in resistant tumour cells comparing to their parental counterparts, and STC2 is upregulated in several other cell lines exposed to TKIs, indicating that STC2 upregulation is a common phenomenon in resistant tumour cells." (PMID 35501821, 2022). "It is suggested that STC2 might be involved in the tumor immune microenvironment by coordinating the activity of specific ICP genes." (PMID 35937984, 2022). "Therefore, it is promising to systematically investigate the clinicopathological importance of serum STC2 levels in tumor diagnosis and in evaluating patients’ prognosis for multiple types of human cancers." (PMID 35501821, 2022). "STC2 enhances tumour metastasis through promoting EMT and upregulating MMP -2 and -9." (PMID 35501821, 2022). "Previous studies showed that STC2 was upregulated in HCC samples, and in vitro experiments suggested that the dysregulation of STC2 could promote tumor cell proliferation and migration." (PMID 35123420, 2022). "The results suggest that STC2 might serve as a promising tumor therapeutic target to improve the immunotherapy response." (PMID 35937984, 2022). "In view of the great importance of circRNAs in HCC, we previously revealed that circ_0011385 enhances HCC cell proliferation and tumor activity via regulation through the miR-361-3p/STC2 axis and that circCRIM1 facilitates HCC progression and angiogenesis by sponging miR-378a-3p." (PMID 35530358, 2022). "Furthermore, the effects of copy number variation (CNV) on STC2 expression were investigated across various tumor types." (PMID 36685853, 2022). "Importantly, STC2 mediates resistance to chemo- and radio-therapies and promotes the development of tumor cell–acquired resistance." (PMID 35937984, 2022). "Moreover, higher expression of STC2 mRNA in tumor tissues was correlated with larger tumor size, presence of venous invasion, lymphatic invasion, distant metastasis, and poorer prognosis of CC patients." (PMID 35734431, 2022). "Therefore, the overexpression of STC2 is positively correlated with tumour growth, invasion, metastasis and patients’ prognosis, highlighting its potential as a biomarker and a therapeutic target." (PMID 35501821, 2022).
tumor (continued). "STC2 is a glycoprotein widely expressed in multiple human tissues and tumor progression." (PMID 36292719, 2022). "In mouse glioma, tumor-infiltrating leukocytes express STC2." (PMID 36078092, 2022). "Additionally, STC2 was closely related to tumor heterogeneity, tumor stemness and tumor immune microenvironment like immune cell infiltration." (PMID 36685853, 2022). "Cell cloning and invasion experiments further confirmed the tumor-promoting function of STC2." (PMID 34422808, 2021). "Therefore, a thorough understanding of the role of STC2 in tumor development and progression is essential to facilitate future studies of this promising marker." (PMID 34612765, 2021). "STC1 and STC2 in various tumor tissues have significantly higher or lower expression levels than those in the corresponding adjacent normal tissues, suggesting that STC may be correlated to the occurrence and development of tumors." (PMID 37287492, 2021). "STC2 is also a tumor marker for several cancers as well as possibly involved in metastasis." (PMID 32411128, 2020). "With STC2's direct correlation with variety of cancers, it is expected that forthcoming studies will help explore the function and regulatory mechanisms of STC2 in tumor progression and metastasis." (PMID 32296395, 2020). "Conversely, some reports showed that STC2 was a tumor suppressor." (PMID 32258098, 2019). "Multifactor Cox survival analysis showed that STC2 expression, tumor diameter, carcinoma emboli in the portal vein, tumor differentiation degree, tumor metastasis, and tumor stage were independent factors affecting the overall survival of postoperative patients." (PMID 30962272, 2019). "The results of the present study showed that the positive expression rate of STC2 in HCC were higher than that of in adjacent tissue, which may indicate the relationship between the occurrence development of tumor and high expression of STC2." (PMID 30962272, 2019). "Given that the PI3K/AKT pathway is reported to promote cell proliferation, migration, invasion, and tumor angiogenesis, behaviors that in turn induce tumor metastasis, we hypothesized that STC2 might promote HNSCC metastasis through the PI3K/AKT pathway." (PMID 27863406, 2017). "Additionally, compared to non-tumor tissue samples, STC2 expression was high in 15.8% (47/298), moderate in 54.7% (163/298), and weak in 29.5% (86/298) of HNSCC cases." (PMID 27863406, 2017). "Similarly the serum STC2 level well correlated with tumor size, lymph node metastasis, and TNM stage of CRC (P < 0.05), which was consistent with the conclusion from tissue STC2 level." (PMID 27662663, 2016). "STC2 protein is also a potential tumor biomarker for CRC diagnosis and prognosis." (PMID 27662663, 2016). "STC2 was further confirmed to enhance tumor growth on CRC-xenograft nude mice." (PMID 27662663, 2016). "Furthermore the elevated STC2 expressions were also confirmed in 77 clinical tumor tissues and sera from CRC patients, and the increased STC2 in tumor tissues and sera correlated with tumor pathologic stage and poor survival for CRC patients." (PMID 27662663, 2016). "This was further emphasized by mRNA analysis of whole tumor preparations, where a significant elevation in hypoxia-related genes (i.e. Glut-1 (Slc2a1), Angpt2, Stc2, and Semaphorin B) could be seen coinciding with reduced CD31-staining." (PMID 26673090, 2015). "STC2, a member of STC family, has been reported to be associated with tumor development." (PMID 25830567, 2015). "The function of STC2 in tumor migration and invasion is also controversial." (PMID 25830567, 2015). "In addition, circulating STC2 mRNA levels correlated with the expressions of STC2 in tumor tissues in LSCC patients." (PMID 24743310, 2014). "From this pilot study, we noticed that some tumor adjacent nasopharyngeal epithelia with normal morphology may have basal levels of STC2 expression." (PMID 24606961, 2014).